CTLA4 (cytotoxic T-lymphocyte associated protein 4)
Diseases named in the same sentence as CTLA4 in open-access papers (continued):
Sharing a sentence is not in itself a finding about the gene and the disease.
tumor (continued). "However, Tumor cells can up-regulate PD-L1 or activate CTLA-4 and this ligand-receptor binding causes inactivation of T cells and tumors escaping the immune response." (PMID 33585182, 2020). "Monoclonal antibodies targeting immune inhibitory receptors including anti‐programmed death receptor‐1 (anti‐PD‐1) and anti‐cytotoxic T‐lymphocyte‐associated antigen‐4 (anti‐CTLA‐4) can reverse T‐cell dysfunction and thus enhance tumor‐specific T‐lymphocyte activity." (PMID 32994997, 2020). "VISTA expression positively correlated with the expression of PD-1, PD-L1, and cytotoxic T-lymphocyte–associated antigen 4 (CTLA-4) in tumor-infiltrating immune cells, suggesting that these molecules simultaneously contribute to evasion of antitumor immunity and play a role in cancer progression." (PMID 32873829, 2020). "Administration of SB-3CT or in combination with CTLA-4 blockade exhibited minimal effects on the body weight of the mice, which further confirmed the limited toxicity associated with SB-3CT treatment in tumor-bearing mice." (PMID 32988398, 2020). "Immunotherapy has continued to establish indications expanding across several cancers in recent years and preliminary clinical data suggest that the cytotoxic T-lymphocyte-associated antigen 4 (CTLA-4) and programmed death 1 (PD-1) inhibitors are promising approaches for tumor managements." (PMID 33046987, 2020). "Immune checkpoint inhibitors (ICIs) are promising new immunotherapeutic drugs that reactivate T cells to kill tumor cells by the blocking programmed cell death protein 1/ligand 1 (PD-1/PD-L1) pathway or the cytotoxic T lymphocyte-associated antigen 4 (CTLA-4) pathway." (PMID 32944393, 2020). "Preliminary observations of patients with recurrent cancers indicate that clinical responses to immune checkpoint blockers are associated with elevated tumor levels of immune inhibitory signals, such as PD-L1, cytotoxic T-lymphocyte-associated protein 4 (CTLA-4) and with increased numbers of TILs." (PMID 32365882, 2020). "In addition, YTHDF2 expression positively correlated with expression of several immune cell markers, including PD-1, TIM-3, and CTLA-4, as well as tumor-associated macrophage gene markers, and isocitrate dehydrogenase 1 in LGG." (PMID 32986017, 2020). "Recent research results show that probiotics such as bifidobacteria can reduce the drug resistance of tumor to programmed cell death protein 1 (PD-1) and cytotoxic T-lymphocyte-associated protein 4 (CTLA-4) molecular-targeted drugs, improve its efficacy, and increase the number of CD8+T cells." (PMID 32455139, 2020). "Also, programmed death ligand 2 (PD-L2) and cytotoxic T-lymphocyte-associated antigen 4 (CTLA-4) were expressed on SGC tumor cells at frequencies of 63% and 74.1%, respectively, whereby PD-L2 expression was associated with a shorter progression-free survival." (PMID 32232506, 2020). "Association of CTLA-4 expression with tumor stage, smoking history, and chemotherapy." (PMID 32850353, 2020). "These underlying mechanisms might contribute to microbial mediation of anti-tumor immune regulation in the context of intestinal inflammation, such as chemotherapy drugs that cause mucositis, or anti-CTLA-4 treatment." (PMID 32522267, 2020). "Similarly, the expression of ICP PD-L1 and CTLA-4 have been previously associated with improved tumor outcomes." (PMID 33374804, 2020). "Furthermore, the response to immunotherapy targeting PD-1 or cytotoxic T lymphocyte-associated antigen (CTLA)-4 varies with gut microbiota composition in both tumour-bearing mice and patients." (PMID 32932843, 2020). "The tumor cells use mechanisms such as the up-regulation of immune checkpoint signaling programmed death-ligand 1 (PD-L1), downregulation of cytotoxic T-lymphocyte-associated protein 4 (CTLA4), and the recruitment of MDSCs, to evade the immune system." (PMID 32517661, 2020).
tumor (continued). "Cytotoxic T-lymphocyte-associated protein 4 and PD-1 antagonists contribute to the progress of effective antitumor immune responses when administered as monotherapy or supplementary therapy, depending on the type of tumor." (PMID 32708748, 2020). "The diversity of TCRαβ repertoire is associated with efficient protection against several pathogens, and more recently, the clonality of both peripheral blood and tumor TCRαβ repertoire has also been associated with improved clinical outcome under anti-PD-1 or anti-CTLA-4 immunotherapy." (PMID 32265933, 2020). "In addition, cytotoxic T lymphocyte-associated antigen 4 (CTLA-4) on tumor cells impacts the function of DCs." (PMID 32784928, 2020). "Undoubtedly, the unleashing of pre-existing anti-tumor immune responses through the blockage of the immune checkpoints—cytotoxic T-lymphocyte-associated protein 4 (CTLA-4) and programmed cell death protein 1 (PD-1)/PD-ligand 1 (PD-L1)—represents the breakthrough of cancer therapy of the last decade." (PMID 32962159, 2020). "Moreover, Tregs in TDLNs and in the tumor expressed high levels of CTLA-4, ICOS, GITR, and OX40, phenotype associated to a high suppressive capacity." (PMID 32601304, 2020). "Then, we applied Gene Ontology (GO), the Kyoto Encyclopedia of Genes and Genomes (KEGG) and CIBERSORT, ESTIMATE algorithm, ssGSEA and somatic mutation analyses to reveal the impact of CTLA4 on the landscape of tumor-infiltrating lymphocytes (TILs) infiltration and genetic mutation." (PMID 33117084, 2020). "The success of antibodies targeting cytotoxic T-lymphocyte-associated protein 4 (CTLA4), programmed cell death 1 (PD-1), or PD-L1 in stimulating immune cell mediated tumor rejection suggests that the immune system is poised for exploitation as a therapeutic target." (PMID 32874188, 2020). "In tumor immunotherapy, successful treatment methods so far have relied on immune checkpoint inhibitors with targets such as programmed cell death protein 1 (PD-1), programmed death ligand 1 (PD-L1), and cytotoxic T-lymphocyte associated protein 4 (CTLA-4)." (PMID 32858811, 2020). "These therapies are based on monoclonal antibodies targeting immunomodulatory receptors such as cytotoxic T-lymphocyte associated protein 4 (CTLA-4) or programmed cell death protein 1 (PD-1) that modulate the activity of cytotoxic T cells, thereby triggering anti-tumor immune responses." (PMID 32466585, 2020). "Meanwhile, the authors found that TNF blockade could further enhance the infiltration of tumor-specific CD8+ T cells into the tumor microenvironment and draining lymph nodes caused by anti–PD-1 and anti–CTLA-4 monoclonal antibody combination therapy." (PMID 32226426, 2020). "However, other immune-suppressive checkpoint genes—including lymphocyte-activation gene 3 (LAG-3) and CTLA-4—and immunosuppressive components—such as T-reg, tumor-associated alveolar macrophages, and tumor-associated neutrophils—were unchanged." (PMID 32380703, 2020). "Previous studies have demonstrated that tumor cells escape from an immune attack by activating certain immune checkpoints, such as cytotoxic T lymphocyte-associated antigen 4 (CTLA-4) and the programmed cell death protein 1 (PD-1), to resist T cell-mediated antitumor immunity." (PMID 31842801, 2019). "In addition, in a series of 956 HCCs, 25% of the samples displayed favorable immune microenvironments for ICIs with CD8+ TILs; high expression of CTLA-4, PD-1 and PD-L1; low Treg infiltration; and few tumor-associated macrophages (TAMs)." (PMID 31892230, 2019). "The genes examined include cellular markers of four immune checkpoint proteins (PD-L1, PD-L2, PD-1, and CTLA-4), immunosuppressive cells (regulatory T cells, tumor-associated macrophages, and myeloid-derived suppressor cells), pan-T lymphocytes, B lymphocytes, and neutrophils." (PMID 31216733, 2019).
tumor (continued). "These include loss of MHC expression, expression of immune-checkpoint proteins such as programmed cell death protein 1 (PD-1) and cytotoxic T-lymphocyte-associated antigen 4 (CTLA-4), as well as the regulation of the local tumor microenvironment to produce an immunosuppressive biochemical milieu." (PMID 31702638, 2019). "Immune checkpoint inhibitors are novel anti-tumor agents, including an anti-cytotoxic T-lymphocyte-associated protein 4 (anti-CTLA4) monoclonal antibody, anti-programmed death 1 (anti-PD1) monoclonal antibody, and anti-programmed death ligand 1 (anti-PDL1) monoclonal antibody." (PMID 30940117, 2019). "The results of several successful immunotherapy trials using an anti-programmed death-1 (PD-1) antibody and combination anti-PD-1/anti-cytotoxic T-lymphocyte associated protein 4 (CTLA-4) show that a significant number of UPS patients experience a reduction in tumor size." (PMID 31096717, 2019). "Tumor and/or immune cells can become immune evasive by expressing immune-regulatory molecules such as the programmed cell death protein 1 (PD-1), programmed death-ligand 1 (PD-L1), or cytotoxic T lymphocyte-associated protein 4 (CTLA-4)." (PMID 31211147, 2019). "Recent years have been associated with striking success in tumor immunotherapy, especially checkpoint inhibitors that target programmed cell death protein 1 (PD-1) / programmed death ligand 1 (PD-L1), and cytotoxic T-lymphocyte-associated antigen-4 (CTLA-4)." (PMID 31377744, 2019). "Here we systemically tested this hypothesis and report that disruption of CTLA-4 recycling underlies both irAE and suboptimal tumor rejection of clinical anti-CTLA-4 antibodies." (PMID 31267017, 2019). "Critically, tumor resident T-reg can highly express cytotoxic T-lymphocyte-associated antigen-4 (CTLA-4), an important checkpoint that acts as a negative regulator of effector T cell (T-eff) activity in vivo, studied in different models including CTLA-4-deficient mice." (PMID 30941125, 2019). "Checkpoint blockade antibodies targeting programmed cell-death protein 1 (PD-1), programmed death-ligand 1 (PD-L1), and cytotoxic T-lymphocyte antigen 4 (CTLA-4) have shown great promise in the clinic, causing complete tumor regression and durable responses in a segment of patients." (PMID 31779705, 2019). "Except Treg depletion, tumor immunotherapy consists of vaccination which causes CTLA-4 blockade." (PMID 30944830, 2019). "Moreover, the TGF-β pathway is linked to tumor immune escape and affects the efficacy of anti-CTLA-4 immunotherapy." (PMID 31739477, 2019). "In recent years, inhibitory checkpoints—including cytotoxic T lymphocyte-associated antigen 4 (CTLA-4), programmed cell death protein-1 (PD-1), and programmed cell death ligand 1 (PD-L1)—have been recognized to suppress anti-tumor immune responses in solid tumors." (PMID 30609841, 2019). "Recently, a series of clinical trials showed that combination of anti-programmed cell death-1 (α-PD-1) and anti-cytotoxic T-lymphocyte-associated protein 4 (α-CTLA-4) could effectively eliminate tumor." (PMID 31673481, 2019). "Cytotoxic T lymphocyte-associated protein 4 (CTLA-4, CD152), expressed on the surface of activated T cells and a subset of Treg cells, functions as an immune checkpoint molecule which can downregulate T cells and inhibit anti-tumor responses." (PMID 31430935, 2019). "Some inhibitory receptors, such as PD-1, lymphocyte activation gene 3 (LAG-3), T cell immunoglobulin mucin 3 (TIM-3), cytotoxic T-lymphocyte-associated protein 4 (CTLA-4), are highly expressed on exhausted T cells during chronic viral infection and tumor progression." (PMID 31632413, 2019). "Genes encoding GM-CSF, an anti-CTLA-4 antibody-like molecule and a number of immune co-stimulatory pathway-activating ligands were then inserted, intending to further enhance the systemic, immune-mediated, anti-tumor effects achieved." (PMID 31399043, 2019).
tumor (continued). "These molecules are expressed on T cells in the tumor microenvironment and inhibit T cell function, including well studied cytotoxic T-lymphocyte associated protein 4 (CTLA-4, also known as CD152) and programmed cell death protein 1 (PD-1, also known as CD279)." (PMID 29857493, 2018). "Notably, positive tumour cell staining for PD-L1 or CTLA-4 has been associated with an inferior OS in GC patients and TILs express PD-1, PD-L1, and CTLA-4 molecules at a significantly higher level compared to the T cells of the peripheral blood." (PMID 29844297, 2018). "Immunomodulatory therapies using monoclonal antibodies to block the co-inhibitory receptors programmed death-1 (PD-1) and cytotoxic T-lymphocyte associated protein 4 (CTLA-4) have revolutionized the treatment of diverse tumor types, including non-small cell lung cancer (NSCLC)." (PMID 30097571, 2018). "CTLA4 restrains the adaptive immune response of T-cells towards tumor-associated antigens." (PMID 29486723, 2018). "Because CTLA-4 is constitutively expressed on CD4+CD25+ Treg, CTLA-4 blockade might be expected to suppress Treg function and allow expansion of a tumor-specific immune response." (PMID 29973204, 2018). "Presently, dual-immune checkpoint inhibition with anti-programmed death receptor-1/programmed cell death receptor- ligand-1 (anti-PD-1/PD-L1) plus anti-cytotoxic T lymphocyte associated antigen-4 (anti-CTLA-4) monoclonal antibodies (MoAbs) is being evaluated for a wide range of tumor histologies." (PMID 29769148, 2018). "Recently, tumor immunotherapies, which is focused on several immune checkpoint molecules, such as programmed cell death-1 (PD-1), programmed cell death-ligand 1 (PD-L1), and cytotoxic T-lymphocyte-associated antigen 4 (CTLA-4), have emerged." (PMID 29556567, 2018). "According to the checkpoint blockade hypothesis, anti-CTLA-4 antibodies cause tumor rejection by promoting priming of naïve T cells through blocking the inhibitory B7-CTLA-4 signaling in peripheral lymphoid organs." (PMID 29713453, 2018). "In contrast, checkpoint inhibitors like CTLA-4 or PD-L1, which may boost but cannot induce anti-tumor immune responses, are frequently associated with significant adverse events, which can be dose limiting." (PMID 29409514, 2018). "While CTLA-4 and PD-L1 are infrequently expressed in PCa, B7-H3 (another B7 superfamily member) is highly expressed in many PCas, may modulate anti-tumor immune responses, and is associated with worse prognosis." (PMID 30400835, 2018). "Overall, tumor-associated CTLA-4 could promotes tumor progression by inhibiting the anti-tumor T cell immunity, inducing tumor-specific T cell apoptosis or impairing cytokine production and T cell-mediated cytotoxicity." (PMID 29682176, 2018). "Immune-checkpoint inhibitors are antibodies against specific immune-checkpoint molecules, such as cytotoxic T-lymphocyte-associated antigen 4 (CTLA-4) and programmed cell death protein (PD-1) and its ligand, that act by avoiding lymphocyte-mediated tumor cell destruction." (PMID 30176934, 2018). "Reasons may be that tumor cells can evade immunomediated recognition through new pathways and PD-1 and CTLA-4 blockade can also cause up-regulation of other immune inhibitory receptors like VISTA and TIM-3." (PMID 29735917, 2018). "In recent years, inhibitory checkpoints, including cytotoxic T lymphocyte–associated antigen 4 (CTLA-4), programmed cell death protein-1 (PD-1), and programmed cell death ligand 1 (PD-L1), have been identified to suppress anti-tumor immune responses in solid tumors." (PMID 29843754, 2018). "Blockade of CTLA-4- and PD-1-mediated immunosuppression promotes restoration of anti-tumor immune function, but if excessive may also pose the risk of tissue damage and autoimmunity." (PMID 29623257, 2018).
tumor (continued). "Cytotoxic T-lymphocyte associated protein 4 (CTLA-4) and programmed death protein 1 (PD-1) and its ligand (PD-L1) are the key proteins that have the capacity to inhibit the responses of T cells that can be tumor promoting." (PMID 30228868, 2018). "Subsequent studies have demonstrated that CTLA-4 is a molecular component expressed on certain tumor cell lines at various degrees of intensity and can cause apoptosis of CTLA-4-expressing tumor cells after interaction with soluble CD80 or CD86 recombinant ligands." (PMID 29672601, 2018). "Preliminary observations of patients with recurrent cancers have indicated that clinical responses to immune checkpoint blockers are associated with elevated tumor levels of immune inhibitory signals, such as PD-L1, CTLA-4 and with increased numbers of tumor-infiltrating lymphocytes (TILs)." (PMID 28977890, 2017). "This may indicate that increased CTLA-4 expression is associated with immunosuppression and acceleration of disease progression and metastasis, possibly mediated by tumor cell synthesis of soluble CTLA-4." (PMID 28707078, 2017). "During the early stage of tumorigenesis, CTLA-4 may elevate the T cell activation threshold, thereby attenuating the antitumor response and elevating tumor susceptibility." (PMID 28099147, 2017). "Furthermore, T cells express inhibitory checkpoint receptors, such as programed cell death protein 1 (PD-1) and cytotoxic T-lymphocyte-associated protein 4 (CTLA-4), which are activated by ligands expressed on pro-tumor immune cells." (PMID 28210259, 2017). "However, a broader picture of the patients’ tumor mutational load along with the status of the immune system as shown for the therapeutic success of anti-CTLA-4 (ipilimumab) is needed to predict a patients’ response to immunotherapy." (PMID 28501851, 2017). "In recent years Tumor immunotherapy has shown promising efficacy, especially in immune checkpoints including inhibitors programmed cell-death protein 1 (PD-1) and cytotoxic T-lymphocyte-associated protein 4 (CTLA-4)." (PMID 28935016, 2017). "A major mechanism through which the tumor-microenvironment exerts its immune-inhibition is inducing the upregulation of surface inhibitory receptors such as cytotoxic T-lymphocyte-associate protein 4 (CTLA-4) and programmed death-1 (PD-1)." (PMID 28331617, 2017). "CTLA4 expression by tumor cells was associated with worse OS and PFS (p=0.05)." (PMID 28038471, 2017). "Elevated frequencies of tumour-associated Tim-3+, CTLA-4+ and PD-1+ CD8 T cells suggests that a subset of patients may benefit from local antibody blockade of these checkpoint inhibitors." (PMID 28423034, 2017). "Vétizou and colleagues have studied another anti-tumor immunotherapy, which relies on the blockade of cytotoxic T lymphocyte-associated antigen 4 (CTLA4), a major negative regulator of T cell activation against a variety of antigens including tumor-associated antigens." (PMID 28632155, 2017). "In 2017, a study of integrated molecular analysis of tumor biopsies, demonstrated that high burden of copy number loss was associated with disease progression despite sequential CTLA-4 blockade, and PD-1 blockade, compared with those biopsies from patients who responded to CTLA-4 blockade." (PMID 29100459, 2017). "Ly6G depletion rescued antigen-specific T-lymphocyte responses and consistently sensitized T-cell inflamed MOC1 tumors to CTLA-4 mAb-induced rejection, suggesting that gMDSCs are the dominant cell type to contribute to immunosuppression associated with tumor progression within this model." (PMID 28915554, 2017). "Examples of immunosuppressive strategies used by tumor cells to escape immune surveillance include elevated activity of Treg cells to inhibit antitumor immune response, upregulation of CTLA-4 and PD-L1; TGF-ß production; and loss of T cell antigen presentation in the tumor." (PMID 26964534, 2016).